Y_RNA (Y RNA )
Gene: Miscellaneous RNA gene on chromosome 16 (11,315,067 to 11,315,178, forward strand). Ensembl gene ENSG00000199668.
Homologues: Orthologues: chimpanzee Y_RNA (96% identical), macaque Y_RNA (92% identical). Paralogues in human: Y_RNA (84% identical), Y_RNA (83% identical), Y_RNA (82% identical), RNY1P5 (81% identical), Y_RNA (81% identical), RNY1P1 (80% identical), Y_RNA (80% identical), Y_RNA (79% identical), RNY1 (79% identical), RNY1P11 (78% identical), RNY1P2 (78% identical), Y_RNA (78% identical), and 94 more.